B2M (beta-2-microglobulin)
Diseases named in the same sentence as B2M in open-access papers (continued):
Sharing a sentence is not in itself a finding about the gene and the disease.
glioma (continued). "We confirmed that B2M played a critical role in tumor progression, patient prognosis and immunotherapy of gliomas." (PMID 33658560, 2021). "A total of 103 glioma tissue samples were collected to determine the distributions of B2M protein levels by immunofluorescent assays." (PMID 33960680, 2021). "In glioma samples, we found that B2M levels in both LGG and GBM samples were higher than those in normal brain tissues." (PMID 33960680, 2021). "We found that both B2M mRNA and protein levels were abnormally upregulated in glioma samples compared with those from normal brain tissue." (PMID 33960680, 2021). "The results revealed that B2M expression was positively correlated with glioma grade and remarkably varied in different IDH1 status groups." (PMID 33960680, 2021). "Isocitrate dehydrogenase (IDH) wild-type gliomas showed upregulated B2M expression with significant difference in LGG samples of grade III." (PMID 33658560, 2021). "B2M was positively related with the high malignant degree of glioma and the poor survival of patients." (PMID 33658560, 2021). "In this study, we found that both B2M mRNA and protein levels were increased in glioma tissue samples compared to those in normal tissue samples." (PMID 33960680, 2021). "The results of GO enrichment analysis revealed that B2M contributed to immune cell infiltration in glioma patients." (PMID 33960680, 2021). "Furthermore, glioma patients with lower B2M expression exhibited significantly longer survival than those with higher levels." (PMID 40842996, 2025). "Moreover, MRI inputs integrated into machine learning models can predict genomic features and differentiate between low- and high-grade gliomas by identifying markers such as B2M, SRPX2, and SERPINH1." (PMID 40806525, 2025). "Glioma patients with high serum B2M levels experienced shorter survival times." (PMID 38844902, 2024). "In addition to above types of tumors, B2M was also abnormally expressed in the glioma, the primary malignant brain tumor with the highest lethality in adults." (PMID 38743119, 2024). "Even in conditions such as Alzheimer's disease, gliomas, and ageing, while recent research indicates a critical role for B2M in these diseases, a more comprehensive understanding of the mechanisms underlying B2M's function in the development and progression of these conditions is imperative." (PMID 38743119, 2024). "Serum B2M might also serve as one of indicators for distinguishing high-grade gliomas and brain metastases." (PMID 38743119, 2024). "B2M is a potential therapy target and can be used to predict poor prognosis in glioma." (PMID 38072118, 2023). "PDIA3 and B2M have been identified as critical immune modulators and hazardous markers in gliomas." (PMID 35418980, 2022). "Next, we also analyzed the correlation between B2M levels and survival times of glioma patients." (PMID 33960680, 2021). "To further gain insight into the mechanisms of B2M in gliomas, we performed KEGG pathway analysis." (PMID 33960680, 2021). "Furthermore, B2M was a moderately sensitive indicator for predicting the mesenchymal molecular subtype of gliomas." (PMID 33960680, 2021). "In contrast, our present study focused on exploring the roles of B2M in glioma immune infiltration." (PMID 33960680, 2021). "And the B2M protein was mainly distributed in the membrane and cytoplasm in glioma cells." (PMID 33960680, 2021). "Furthermore, GO(Gene‐ontology) enrichment and immune infiltration analysis were employed to investigate the probable roles of B2M in gliomas." (PMID 33960680, 2021). "We speculated that B2M might potentially regulate immunosuppression via the in-depth interplay with immune checkpoint molecules in tumor microenvironment in gliomas." (PMID 33658560, 2021). "Subsequent HPA dataset results also indicated that B2M protein was upregulated in glioma patients." (PMID 33960680, 2021).
glioma (continued). "Additionally, B2M potentially participated in the inflammatory response in the glioma microenvironment, interacted with other immune checkpoint molecules, and suppressed the anti-tumor immunity." (PMID 33658560, 2021). "In the present study, we focused on exploring the roles of B2M in glioma immune infiltration." (PMID 33960680, 2021). "However, experimental studies were essentially needed for further validation of its therapeutic value and regulatory role in immune related responses in gliomas before any attempt to target B2M in a clinical setting." (PMID 33658560, 2021). "Glioma patients with high B2M expression had worse prognosis in several molecular subgroups." (PMID 33658560, 2021). "Results showed that B2M to be an independent predictive marker in glioma patients." (PMID 33960680, 2021). "The relationship between B2M and seven inflammatory activity related signatures was then explored in pan-gliomas and LGG, B2M expression had positive correlation with HCK, LCK, MHC-I, MHC-II, STAT1 and interferon metagenes, and negative correlation with IgG metagene expression." (PMID 33658560, 2021). "Interestingly, glioma patients with lower B2M expression had remarkably longer survival times than those with higher B2M expression." (PMID 33960680, 2021). "In addition, other chemokines that are highly correlated with B2M expression also participate in different roles in glioma immune infiltration." (PMID 33960680, 2021). "B2M was significantly downregulated in methylated samples in pan-gliomas and LGGs." (PMID 33658560, 2021). "Moreover, results from the HPA database also showed that B2M protein expression was higher in glioma tissues, especially in GBMs, compared with that in normal tissues." (PMID 33960680, 2021). "Next, we further investigated the clinical significance of B2M in glioma patients." (PMID 33960680, 2021). "Furthermore, B2M protein was mainly distributed in the plasma membrane and cytoplasm in glioma cells." (PMID 33960680, 2021). "Therefore, our subsequent study will focus on exploring the effects of B2M inhibition on glioma immune cell infiltration and survival times in glioma patients." (PMID 33960680, 2021). "Finally, KEGG(Kyoto Encyclopedia of Genes and Genomes) pathway and co‐expression analysis were conducted to determine potential mechanisms of B2M in gliomas." (PMID 33960680, 2021). "Taken together, B2M could potentially mediate immune and stromal cell infiltration in gliomas microenvironment." (PMID 33658560, 2021). "The pooled hazard ratio along with the 95% confidence interval for the association between low B2M expression and overall survival in 1921 cases of glioma patients was 0.43 (0.35–0.54), with no significant heterogeneity among the three datasets." (PMID 33960680, 2021). "Our present study also showed that high B2M expression could mediate high immune infiltration in gliomas." (PMID 33960680, 2021). "Taken together, these results revealed that B2M might function as an independent prognostic indicator for gliomas." (PMID 33960680, 2021). "Taken together, these results revealed that B2M might function as an independent prognostic indicator for glioma patients." (PMID 33960680, 2021). "In addition, using bioinformatics methods, we analyzed multiple publicly available glioma databases and found that B2M might promote glioma progression by modulating the tumor immune microenvironment." (PMID 38743119, 2024). "In addition, results of KEGG pathway analysis and co‐expression analysis suggested that B2M may mediate glioma immune infiltration via chemokines." (PMID 33960680, 2021). "The upregulation of B2M in gliomas and its relation to an immune suppressive tumor microenvironment indicated that B2M might be a prospective prognostic marker and therapeutic candidate in gliomas." (PMID 33658560, 2021). "In addition, B2M was highly enriched in CL and ME subtypes of gliomas and could be used as a predictor with high sensitivity for gliomas." (PMID 33658560, 2021).
glioma (continued). "Additionally, we also evaluated the distribution of B2M in different molecular subtypes of gliomas." (PMID 33960680, 2021). "Additionally, a meta‐analysis was performed to assess whether B2M could be used as a predictive marker for glioma patients." (PMID 33960680, 2021). "Thus, we conclude that B2M might decrease the survival times of glioma patients, at least in part due to mediating high immune infiltration." (PMID 33960680, 2021). "Therefore, expression patterns of B2M in serum are similar to those in glioma tissues." (PMID 33960680, 2021). "Moreover, meta‐analysis showed that B2M was an independent predictive marker in glioma patients." (PMID 33960680, 2021). "Thus, inhibitors targeting the B2M in combination with other immune checkpoint molecules may revolutionize the treatment of gliomas." (PMID 33658560, 2021). "Therefore, the high expression of immune checkpoint molecules might represent an immune suppressive microenvironment that was more likely to exist in gliomas with high B2M expression." (PMID 33658560, 2021). "In addition, B2M levels in IDH1 mutant glioma (weak intensity 58.7%; moderate intensity 37%; strong intensity 4.3%) samples were lower than those in IDH1 wild‐type (weak intensity 14%; moderate intensity 40.4%; strong intensity 45.6%) samples(Z = −5.534, p < 0.01)." (PMID 33960680, 2021). "In pan-glioma and LGG samples, B2M positively correlated with immune, stromal and ESTIMATE scores, and the correlation was significant." (PMID 33658560, 2021). "A large cohort of patients with gliomas from the TCGA, CGGA, and Gravendeel databases was included to explore differential expression patterns and potential roles of B2M in gliomas." (PMID 33960680, 2021). "Thus, we speculated that B2M might mediate glioma immune infiltration via chemokines." (PMID 33960680, 2021). "Apart from the B2M was abnormally upregulated, other recent reported molecules such as NUSAP1, Paxillin, CAVIN1, and PARP9 also overexpressed in glioma tissues." (PMID 33960680, 2021). "B2M exhibited a highly positive correlation with immune checkpoint molecules, such as PDCD1LG2, HAVCR2, CD274 in pan-gliomas and LGG samples, respectively." (PMID 33658560, 2021). "In pan-gliomas and LGGs from TCGA dataset, disease-specific survival (DSS), overall survival (OS), and progression-free interval (PFI) of patients with high B2M were significantly shorter than those with low B2M." (PMID 33658560, 2021). "In this review, we provide a comprehensive summary and discussion of recent advances in understanding the pathological processes involving B2M in CNS diseases (e.g., Alzheimer's disease, aging, stroke, HIV-related dementia, glioma, and primary central nervous system lymphoma)." (PMID 38743119, 2024). "B2M, a non-glycosylated protein, is mainly distributed in the cell membrane and cytoplasm of glioma cells and is highly expressed in GBM." (PMID 37759870, 2023). "However, a comprehensive analysis of B2M in the prognosis and immune microenvironment of gliomas has not yet been reached." (PMID 33658560, 2021). "After adjusting for the influence of glioma purity, we found that high expression of B2M in LGGs was correlated with high levels of infiltration of B cells, CD8+ T cells, CD4+ T cells, macrophages, NK cells, and dendritic cells, while low expression of B2M yielded opposite results." (PMID 33960680, 2021). "Furthermore, B2M in GSCs could activate the PI3K/AKT/MYC signaling axis to stimulate TGF-β1 secretion, thereby induced AKT pathway activation in macrophages to promote their polarization into M2 types, which, in turn, facilitated glioma progression." (PMID 38743119, 2024). "Following stimulation with EGFRvIII-expressing glioma, we demonstrated that both control (i.e., T cells edited for TRAC and B2M, without CAR) and CART-EGFRvIII cells (i.e., T cells edited for TRAC and B2M, with CAR) were positive for surface PD-1 by flow cytometry." (PMID 31727131, 2019).
anemia (16 papers, 2014 to 2026). A reduction in the number of red blood cells, the amount of hemoglobin, and/or the volume of packed red blood cells. "Results: the FcγRIIIA-158 V/V homozygous genotype was associated with high-risk cytogenetics, anemia, high beta-2 microglobulin levels, and more than 10 osteolytic lesions." (PMID 41976307, 2026). "B2m and Hrg also have iron transport ability; their absence will lead to severe anemia and tissue iron overload." (PMID 36389720, 2022). "Compared to patients without +1q, those with +1q at diagnosis were more likely to present with anemia, thrombocytopenia, high disease burden as signified by beta-2-microglobulin, and higher ISS stage." (PMID 31767829, 2019). "Patients with +1q were more likely to present with anemia and/or thrombocytopenia, had higher beta-2-microglobulin, and had a higher ISS and R-ISS stage." (PMID 31767829, 2019). "Elevated beta-2 microglobulin and anemia are common abnormalities at presentation." (PMID 39776709, 2024). "Similar findings have been reportedwith Chronic Lymphocytic Leukemia, as black patients present with high-riskprognostic markers, severe anemia, increase in beta-2 microglobulin levels, advancedRai staging, and cytogenetic markers associated with a worse prognosis as comparedto white patients." (PMID 33834180, 2021). "Patients with TINU have been reported to have anemia, eosinophilia, elevations in ESR and CRP, sterile pyuria and abnormal elevations in serum, and urine beta-2 microglobulin." (PMID 26446047, 2015). "After failing additional chemotherapy, she was treated with single agent dose-escalated R for 1 year, and achieved PR/SD with no clinical features of illness, and resolution of anemia and stable, abnormal serum immunoglobulins and normal beta-2 microglobulin." (PMID 28203581, 2017).
COVID-19 (15 papers, 2020 to 2025). A disease caused by infection with severe acute respiratory syndrome coronavirus 2. "The beta-2-microglobulin (B2M) gene pathway is associated with COVID-19 and other infectious diseases." (PMID 41301889, 2025). "In addition, in the context of COVID-19 myocarditis patients from the GSE183850 dataset, B2M and C3 were established as diagnostic markers that were subsequently validated (AUC = 0.978 and AUC = 0.956, respectively)." (PMID 40230577, 2025). "Regardless of the tissue type, we saw consistent increases in genes such as B2M, CD81, GNAS, HLA.B, HSPA1A, HSPB1, and SERPING1 in COVID-19 lungs." (PMID 35233546, 2022). "Further to these ligands, we also noted increased expression of EREG, OSM, B2M, as well as type II HLA molecules HLA-A, HLA-B, HLA-C, and HLA-E predominantly in CD4+ and CD8+ T cells and monocytes in patients with severe COVID-19." (PMID 33458558, 2021). "Unsurprisingly, the “near to epithelial cell” myeloid population shows higher COVID-19 signatures score and highly expresses multiple MHC Class I and II related genes, such as B2M, HLA-A, HLA-B, HLA-C, HLA-E, and HLA-DRA, which are associated with the interferon (IFN) response." (PMID 37120608, 2023). "In the presence of B2M internal control, the fluorescence signal of pan-SARS-E remained high for the detection of COVID-19-confirmed human clinical samples and did not generate an interference signal." (PMID 37275136, 2023).
ovarian carcinoma (14 papers, 2014 to 2024). A malignant neoplasm originating from the surface ovarian epithelium. "B2M elevation is often associated with increased cell proliferation, making B2M a valuable biomarker for ovarian cancer diagnosis." (PMID 40836974, 2024). "OVA1 is an FDA-approved blood test that measures the levels of five proteins (CA125, transferrin, transthyretin, apolipoprotein A1, and beta-2 microglobulin) to detect ovarian cancer risk in women." (PMID 36232415, 2022). "This study was performed to examine the expression of B2M in different histopathological types of ovarian tumours, to explore the function of B2M in ovarian cancer (OC) cells and to investigate the mechanisms underlying the regulation of B2M by the TGF-β signaling pathway." (PMID 26983758, 2016). "Therefore, it is conceivable that B2M mutations are a rare cause of HLA deficiency in ovarian cancer and in this respect the B2M-defective OC316 cell line may represent an infrequent genotype of this tumor." (PMID 27683036, 2016). "The levels of expression of antigen expression genes TAP1, TAPBP, B2M, and HLA-A (the human ortholog of the mouse H2-D1 gene) were shown to predict longer patient survival in colon and ovarian cancers." (PMID 39388288, 2024). "In vitro analysis using SKOV3 ovarian cancer cell line emphasized that B2M knock-down resulted in a decreased cell proliferation, migration and invasion, and an antibody against B2M induced apoptosis." (PMID 36338962, 2022). "DNMT inhibitors can play an anti-tumor role in colon and ovarian cancer by up-regulating B2M and CALR." (PMID 34910788, 2021). "Nevertheless, our findings, coming together with recent evidences from other laboratories, support the notion that B2M is a potential marker for the diagnosis of OC, especially the epithelial-type borderline and malignant tumours of the ovary." (PMID 26983758, 2016). "Our findings suggest that B2M is a potential tissue biomarker and therapeutic target of borderline and malignant ovarian tumours and the dysregulation of B2M in these tumours may be mediated by the TGF-β signaling pathway." (PMID 26983758, 2016). "B2M was overexpressed in human epithelial-type borderline and malignant tumours of the ovary." (PMID 26983758, 2016). "Indeed, another study reported that none out of 21 ovarian cancers tested showed defects of B2M, while heavy chain haplotype loss has been reported as a cause of tumor escape in metastases from this tumor." (PMID 27683036, 2016). "Treatment of cancer cells with 5-AC also leads to significant re-expression of B2M, CALR, CD58, PSMB8, and PSMB9 at both the RNA and protein level in the colon and ovarian cancer cell lines." (PMID 28622390, 2017). "Here we show that one out of 6 ovarian cancer cell lines had an IFN-γ- and IL-27-resistant HLA-null phenotype, due to the same defect of the B2M gene." (PMID 27683036, 2016). "However, the clinical development of TTR, B2M and APOA1 as biomarkers for ovarian cancer is still ongoing." (PMID 40836974, 2024). "B2M is a small, non-glycosylated polypeptide elevated in ovarian cancer and critical to mediating tumorigenesis, metastasis, and angiogenesis through various signaling pathways." (PMID 40836974, 2024). "Additionally, multiplexed magnetic nanoparticle-antibody conjugates combining MUC16, B2M, and APOA1 achieved high sensitivity (94%) and specificity (98%) in distinguishing early-stage ovarian cancer patients from healthy individuals." (PMID 40836974, 2024). "AGPAT1, B2M, BASP2, IER3, and IL1B are the salivary mRNAbiomarkers for ovarian cancer detection." (PMID 37693919, 2022). "We confirm that treatment with DNMT inhibitors upregulates expression of the antigen processing and presentation molecules B2M, CALR, CD58, PSMB8, PSMB9 at the RNA and protein level in a wider range of colon and ovarian cancer cell lines and treatment time points than had been described previously." (PMID 28622390, 2017).